ADIPOR2 (adiponectin receptor 2)
Diseases named in the same sentence as ADIPOR2 in open-access papers (continued):
Sharing a sentence is not in itself a finding about the gene and the disease.
Obesity (continued). "Collectively, these results demonstrate that AdipoR1 and AdipoR2 exhibit overlapping and distinct effects in skeletal muscle consistent with enhanced adiponectin sensitivity but these appear insufficient to ameliorate established obesity-induced adiponectin resistance." (PMID 28145500, 2017). "The findings of the study demonstrated that BCP reduced obesity-related AHR by inhibiting macrophage polarisation, activating AMPK, activating Nrf2/HO-1, increasing AdipoR1 and AdipoR2 expression, and decreasing NFB expression in the lungs of animals." (PMID 37251328, 2023). "In this sense, the adiponectin receptors AdipoR1 and AdipoR2 (which, like OR83B, have an inverted membrane topology) are decreased in animal models of obesity and type 2 diabetes." (PMID 34860303, 2022). "In obesity, adiponectin resistance is increased with reduced expression of adiponectin receptors (ADIPOR1 and ADIPOR2) in breast cancer cells." (PMID 34367982, 2021). "Considering that serum ADIPOQ concentration and its skin expression were altered in obesity, these findings suggest that ADIPOQ’s effects on skin are at least in part regulated by the reduced expression of ADIPOR2." (PMID 34438765, 2021). "Adiponectin and its signaling through the receptors AdipoR1 and AdipoR2 rank highly in the ongoing search for the holy grail that might improve insulin sensitivity, modulating inflammatory responses, and regulating energy metabolism in patients with obesity and/or Type 2 Diabetes (T2D)." (PMID 28271029, 2017). "In adipose tissue, we found not only a number of known cancer-related genes, like SOD2 or AMACR, but also diabetes- and obesity-related genes, like MTHFR or ADIPOR2." (PMID 23889843, 2013). "This outcome demonstrates a negative correlation between the ADIPOQ and ADIPOR2 levels expressed in the skin and in the body fat mass that is the obesity condition." (PMID 34438765, 2021). "The fact that AdipoR2-/-ApoE-/- mice and AdipoR2+/+ApoE-/- controls were comparable in terms of body weight gain or obesity in this study is however not surprising since ApoE-deficiency has been shown to attenuate diet-induced obesity in mice." (PMID 24324556, 2013). "Because of the potential effect of obesity on adiponectin receptor expression we compared the proportions of follicles in women with PCO that expressed Adipo R1 and AdipoR2 in theca in women who were overweight or obese with expression in theca from lean PCO subjects." (PMID 24260388, 2013). "We have also previously demonstrated that 6 h of adiponectin treatment in human primary myotubes derived from lean individuals increases AdipoR1 but not AdipoR2 mRNA expression, whereas myotubes derived from individuals who had obesity or obesity and diabetes did not alter AdipoR1 or AdipoR2." (PMID 36232744, 2022).
diabetes (22 papers, 2011 to 2025). "We then validated the protein expression of AdipoR1 and AdipoR2 in murine and cellular models of diabetes." (PMID 41146365, 2025). "AdipoRon treatment restored the diabetes-induced decreases in intracardiac AdipoR1 and AdipoR2 expressions to levels comparable to those in control db/m mice." (PMID 35351872, 2022). "This echoes results reported in a previous study proposing that increased insulin sensitivity upon AdipoRon treatment can restore diabetes-induced decrease in renal and cardiac AdipoR1 and AdipoR2 expression to the levels present in control db/m mice." (PMID 34214600, 2021). "Compared with the control group, adiponectin, adipoR1, and adipoR2 showed significantly increased protein expression levels in the diabetes group (P < 0.05 for adipoR1 and adipoR2 and P < 0.001 for adiponectin)." (PMID 25525608, 2014). "In summary, this study demonstrated that, in the early stages of STZ-induced diabetes, rats displayed APN deficiency and increased inflammatory cytokines together with reduced cardiac AdipoR2 expression and impaired Akt-eNOS and STAT3-eNOS activation." (PMID 21912612, 2011). "The combination of NAC and ALP confer a synergistic effect on restoration of APN content and AdipoR2 mediated eNOS activation, which is a potential mechanism for enhancing the resistance to MI/R injury in the early stage of diabetes." (PMID 21912612, 2011). "Studying the C. elegans homologs of the anti-diabetic adiponectin receptors (AdipoR1 and AdipoR2) has led us to exciting new discoveries and to revisit what may be termed “The Membrane Theory of Diabetes”." (PMID 27671740, 2016). "The results suggest that cardiac APN may be a major contributor to the restoration of cardiac AdipoR2 expression in diabetes." (PMID 21912612, 2011). "Taken together, these findings suggest that enhancements of APN and cardiac AdipoR2 may represent the major mechanisms by which NAC or NAC and ALP combination confer cardioprotection in early diabetes." (PMID 21912612, 2011). "We examined whether genetic variation in ADIPOR2 predicts the development of cardiovascular disease (CVD) and/or Type 2 Diabetes (T2DM) in individuals with impaired glucose tolerance (IGT) participating the Finnish Diabetes Prevention Study (DPS)." (PMID 21943112, 2011).
breast cancer (19 papers, 2008 to 2023). A primary or metastatic malignant neoplasm involving the breast. "Survival analysis between these two groups showed that AdipoR2 was significantly associated with poor RFS in breast cancer patients (P = 0.011)." (PMID 37454080, 2023). "Although AdipoRs expression was markedly increased in breast tumor tissues compared with control tissues, it has been shown that the high expression of AdipoR2 in breast cancer tissue is significantly and positively associated with vascular and lymph vascular invasion." (PMID 37240258, 2023). "Our overarching hypothesis was that higher IHC expression of LEP, LEPR, ADIPOQ, ADIPOR1, and ADIPOR2 within the breast tumor microenvironment is associated with breast cancer aggressiveness, but we generally observed the opposite." (PMID 32046756, 2020). "The tumor with the highest frequency of ADIPOR1 alteration is breast cancer, while the tumor with the highest frequency of ADIPOR2 alteration is ovarian epithelial tumor." (PMID 36896172, 2023). "Patients with AdipoR2-high breast cancer display significantly shorter relapse-free survival (RFS) than those with AdipoR2-low breast cancer." (PMID 37454080, 2023). "Emphatically, knockdown of adiponectin receptor 1 (AdipoR1) and AdipoR2 impaired the proliferation and invasion of breast cancer cells." (PMID 37454080, 2023). "We analysed samples from 113 preoperative breast cancer patients and performed IHC to evaluate the level of AdipoR1 and AdipoR2." (PMID 37454080, 2023). "We used immunohistochemistry (IHC) to assess LEP, LEPR, ADIPOQ, ADIPOR1, and ADIPOR2 expression in breast tumor tissue microarrays among a sample of 720 women recently diagnosed with breast cancer (540 of whom self-identified as Black)." (PMID 32046756, 2020). "There are two adiponectin receptor subtypes, AdipoR1 and AdipoR2, which have been identified in mammalian tissues, including human cancer cell lines and also in human mammary tumors." (PMID 32215366, 2019). "Indistinctly of the molecular classification of breast cancer of the cell lines used, they all express leptin, adiponectin, AdipoR1, and AdipoR2." (PMID 29311755, 2017). "As for the expression assay, in MCF-7 breast cancer cells, the expression of mRNA of AdipoR2 (2.423 ± 2.35) was greater than the expression of AdipoR1 (1.679 ± 1.76)." (PMID 29311755, 2017). "Immunohistochemical studies have shown that leptin, adiponectin and their receptors (Ob-R, AdipoR1 and AdipoR2) are detected in the cytoplasm of MCF-7 breast cancer cells." (PMID 23750285, 2013). "We have been able to show that five different breast cancer cell lines express either AdipoR1 and/or AdipoR2 protein." (PMID 18182989, 2008). "ADIPOR2 protein was dysregulated in breast cancer and hepatocellular carcinoma." (PMID 36896172, 2023). "A more specific biological pathway may involve the upregulation of receptors AdipoR1 and AdipoR2 in dendritic cells of advanced breast cancer, leading to impaired T-cell immune response." (PMID 34876619, 2021). "The molecular mechanisms underlying the association between increased adiposity and aggressive breast cancer phenotypes remain unclear, but likely involve the adipokines, leptin (LEP) and adiponectin (ADIPOQ), and their receptors (LEPR, ADIPOR1, ADIPOR2)." (PMID 32046756, 2020). "In addition, we reported protein expression levels of AdipoR1, AdipoR2 and adiponectin in the mammary tumor (MT), mammary fat pad (MFP) and liver tissues in relationship to serum adiponectin levels in this breast cancer mouse model." (PMID 32215366, 2019). "Cytoplasmic expression of both the AdiopRs is known in normal breast epithelial and breast cancer cells but breast cancer tissue exhibits a higher expression of AdipoR2 which also significantly and positively correlates with vascular and lymphovascular invasion in breast cancer." (PMID 31121868, 2019).
breast cancer (continued). "The reduction in the expression of AdipoR1 mRNA and the increase in the expression of AdipoR2 mRNA could indicate that the effective receptor for the in vivo signaling of adiponectin in breast cancer tissue is AdipoR1." (PMID 29311755, 2017). "The adiponectin receptor ADIPOR2 was found to be expressed in human breast cancer cells." (PMID 25004928, 2014). "The adiponectin receptors, AdipoR1 and AdipoR2, have been detected in human breast cancer specimens, but not clearly associated with other biomarkers." (PMID 21974986, 2011). "Interestingly, high expression of adiponectin, adiponectin receptor 2 (ADIPOR2), and beclin 1 (BECN1, the protein implicated in the autophagic programmed cell death), significantly correlated with increased overall survival in chemotherapy-treated breast cancer patients." (PMID 36555323, 2022). "Expression levels of adiponectin, AdipoR1 and AdipoR2 proteins were measured in the mammary fat pad (MFP), mammary tumor (MT) and liver tissues from 74 weeks old MMTV-TGF-α transgenic mice with and without MT using Western Blot." (PMID 32215366, 2019). "With regard to the expression of AdipoR1 and AdipoR2 mRNA in HCC1937 breast cancer cells, as in the case of MCF-7 cells, the expression of AdipoR2 mRNA (1.336 ± 0.905) was greater than the expression of AdipoR1 (1.181 ± 0.67)." (PMID 29311755, 2017). "It has been demonstrated by several groups that human breast cancer cells including MDA-MB-231 and MCF-7 cells have detectable levels of adipoR1 and adipoR2 proteins." (PMID 23691032, 2013). "Our results also indicate AdipoR2 protein was expressed by MCF-7, T47D, MDA-MB-231, and MDA-MB-361 breast cancer cells." (PMID 18182989, 2008). "Comparison of adipokines and their receptors (AdipoR1, AdipoR2 and Ob-R), COXs, aromatase, F2-isoprostanes, prostaglandin F2α, α-SMA and aromatase in breast tissues adjacent to the tumor and tumor tissues of breast cancer patients on the basis of percent of staining area." (PMID 26431176, 2015). "Comparison of adipokines and their receptors (AdipoR1, AdipoR2 and Ob-R), COXs, F2-isoprostanes and prostaglandin F2α, α-SMA and aromatase in the breast tissues adjacent to the tumor and tumor tissues of breast cancer patients on the basis of staining intensity." (PMID 26431176, 2015). "This study describes the direct expression/localization of Ki67, COXs, aromatase, eicosanoids, adipokines and their receptors (Ob-R, AdipoR1 and AdipoR2), β-catenin and α-SMA in breast cancer specimens using immunohistochemistry and correlated with pathological parameters." (PMID 26431176, 2015). "Some previous reports suggested that cytostatic effects of adiponectin in breast cancer cells are primarily mediated through AdipoR1, and our results with AdipoR2-negative cells and AdipoR2-knockdown cells confirm this notion." (PMID 21974986, 2011). "Interestingly, adiponectin receptors are known to be differently expressed in breast cancer cell lines independent of ERα status, with a higher expression of AdipoR1 in MCF-7, T47D and MDA-MB-231 cells, and a higher level of AdipoR2 in MDA-MB-361 cells." (PMID 37240258, 2023).
type 2 diabetes (18 papers, 2010 to 2025). "Variants in ADIPOQ, the gene encoding adiponectin, have been shown to influence serum adiponectin concentration, and along with variants in the adiponectin receptors (ADIPOR1 and ADIPOR2) have been implicated in metabolic syndrome and type 2 diabetes." (PMID 23351195, 2013). "Sixty-four tagging single nucleotide polymorphisms in ADIPOQ, ADIPOR1 and ADIPOR2 were genotyped in two general population cohorts consisting of 2,355 subjects, and one cohort of 967 subjects with type 2 diabetes." (PMID 23351195, 2013). "In particular, ADIPOR2 variants have been strongly associated with type 2 diabetes in the Old Amish Order and in a Chinese population." (PMID 20178558, 2010). "More specifically, in a genetic association analysis in the French population, rs767870 was the only genetic marker associated with type 2 diabetes of the 12 ADIPOR2 SNPs studied." (PMID 20178558, 2010). "It is of particular interest that three different studies have identified the rs767870 variant of the ADIPOR2, as being associated either with triglyceride levels and fat accumulation or as a determinant of type 2 diabetes." (PMID 20178558, 2010). "Also, variations in ADIPOR2 have previously been demonstrated to be associated with type 2 diabetes." (PMID 32366212, 2020). "Furthermore, variants in the gene encoding one of the adiponectin receptors (ADIPOR2) were reported to be associated with increased risk of developing type 2 diabetes and greater cardiovascular disease risk factors in individuals with glucose intolerance." (PMID 24225161, 2013). "Advanced investigation should be conducted to demonstrate whether the receptors for adiponectin, such as ADIPOR1 and ADIPOR2, have an impact on the risk of developing type 2 diabetes and CAD in a special race." (PMID 23590551, 2013). "In adipose tissue, Blüher and co-workers also reported an upregulation of ADIPOR2 in the subcutaneous and visceral fat of obese and type 2 diabetic patients." (PMID 39058075, 2024). "Patients affected by impaired glucose tolerance and type 2 diabetes showed reduced ADIPOR2 mRNA expression in subcutaneous fat, whereas ADIPOR1 mRNA was higher." (PMID 34438765, 2021). "Deletion of the gene entirely in mice models demonstrates ineffective ADIPOR2 function in development of type 2 diabetes, and recovery of receptor function has been considered for a potential target in preventing diabetic nephropathy in mice." (PMID 32366212, 2020). "ADIPOR1 and ADIPOR2 are considered promising genes for type 2 diabetes, the metabolic syndrome and its complications, such as cardiovascular disease." (PMID 20178558, 2010). "An in vitro study using AdipoR1 and AdipoR2 siRNAs in HCMs highlighted the same significant role-play assigned to both AdipoR1 and AdipoR2 in exerting cardioprotective effects under the presence of excess HG and PA media, which mimics the condition similar to type 2 diabetes." (PMID 35351872, 2022). "AdipoRon-induced expression of AMPK, PPARα, PGC-1α, and Nrf2 through both AdipoR1 and AdipoR2 are involved in regulating MCT1/2/4 and may support cellular functions by increasing lactate and ATP levels in the sciatic nerve in type 2 diabetic mice." (PMID 40671105, 2025). "It is unknown whether the expression of adipoR2 and NADPH oxidase subunits in the heart and the expression of adipoR1 in aorta are changed by telmisartane treatment in type 2 diabetic rats." (PMID 22873349, 2012). "This study investigated the effect of telmisartan on the expression of adiponectin receptor 2 (adipoR2) and nicotinamide adenine dinucleotide phosphate (NADPH) oxidase subunits in the heart and the expression of adiponectin receptor 1 (adipoR1) in aorta in type 2 diabetic rats." (PMID 22873349, 2012). "The expression levels of AdipoR1 and AdipoR2 in skeletal muscle, as well as plasma adiponectin concentrations, have been described to be lower in individuals with a family history of type 2 diabetes mellitus (T2DM) than in those with no family history." (PMID 25650072, 2015).
Glucose intolerance (15 papers, 2013 to 2025). Glucose intolerance (GI) can be defined as dysglycemia that comprises both prediabetes and diabetes. "AdipoR1/AdipoR2 double-KO mice present glucose intolerance and hyperinsulinemia, demonstrating the key roles of these receptors in the physiological regulation of glucose metabolism and insulin sensitivity." (PMID 27822289, 2016). "Deletion of AdipoR1 blocked the adiponectin-mediated phosphorylation of AMPK, while AdipoR2 gene deletion increased adiposity and glucose intolerance, presumably due to increased gluconeogenesis." (PMID 26064110, 2015). "AdipoR2-null mice demonstrated a hindered adiponectin-mediated PPAR-α activation and unlike AdipoR1-deficient mice showed resistance to diet-induced glucose intolerance." (PMID 26064110, 2015). "AdipoRon showed very similar effects to adiponectin in muscle and liver, such as an activation of AMK and PPARα pathways, and ameliorated IR and glucose intolerance in mice fed a high-fat diet, which was completely obliterated in adipoR1 and AdipoR2 double-knockout mice." (PMID 24864249, 2014). "In addition, AdiopR1-null mice have increased adiposity with augmented glucose intolerance, whereas AdipoR2-null mice are lean and resistant to diet-induced glucose intolerance." (PMID 23667684, 2013).
metabolic syndrome (11 papers, 2006 to 2026). A cluster of metabolic risk factors for CARDIOVASCULAR DISEASES and TYPE 2 DIABETES MELLITUS. "Adiponectin receptor 2 (AdipoR2), best known for its role in preventing metabolic syndrome, is an evolutionarily conserved protein critical for cell membrane homeostasis." (PMID 41327238, 2025). "Mouse mutants lacking either or both AdipoR1 and AdipoR2 are without obvious phenotypes when maintained under normal conditions but develop metabolic syndrome symptoms when challenged with high fat diets." (PMID 27082444, 2016).